FASN (fatty acid synthase)
Diseases named in the same sentence as FASN in open-access papers (continued):
Sharing a sentence is not in itself a finding about the gene and the disease.
lung carcinoma (continued). "The majority of studies have reported that FASN induces EMT in cancer cells; however, some studies have shown that FASN-induced EMT can be inhibited in breast and lung cancer cells by rewiring the metabolic state of the cells." (PMID 31027222, 2019). "FASN was involved in glucose metabolism via down-regulation of the AKT/ERK pathway and eventually altered the malignant phenotype in lung cancer cells." (PMID 31122252, 2019). "Fatty acid synthase (FASN) and carnitine palmitoyltransferase 1c (CPT1C) are FA metabolism enzymes that have also been reported to be elevated in lung cancer." (PMID 23936004, 2013). "To further investigate the implications of FASN inhibition in lung adenocarcinoma, we have analyzed the blockage of FASN by EGCG and C75 in A549 lung cancer cells." (PMID 22769244, 2012). "We characterize and compare the anti-cancer effects of the FASN inhibitors C75 and (−)-epigallocatechin-3-gallate (EGCG) in a lung cancer model." (PMID 22769244, 2012). "We evaluated in vitro the effects of C75 and EGCG on fatty acid metabolism (FASN and CPT enzymes), cellular proliferation, apoptosis and cell signaling (EGFR, ERK1/2, AKT and mTOR) in human A549 lung carcinoma cells." (PMID 22769244, 2012). "High levels of fatty acid synthase (FAS) expression have been observed in several cancers, including breast, prostate, colon and lung carcinoma, compared with their respective normal tissue." (PMID 16969344, 2006). "Additionally, we observed elevated intracellular lipid droplets in Y5Rhigh-tumor cells in correlation with increased levels of ERK, SREBP2, FASN and CPT1 in clinical samples of lung cancer brain metastasis and in patient-derived brain-metastatic xenografts." (PMID 40595538, 2025). "We also found that miR-195 could directly bind to the mRNAs of SREBF1, FASN and ACACA in lung cancer cells resulting in decreases in lipid droplet formation induced by PM2.5 exposure." (PMID 36496421, 2022). "Such simultaneous augmentation suggests that the lipid demand for cell growth and proliferation of lung cancer is huge, and probably neither of them alone can meet the need, as fatty acid synthase inhibitor treatment is generally harmful to cancer cells." (PMID 36293388, 2022). "Another study linking SUMO activity with dysregulated-lipid metabolism in cancer shows that, in specific human-derived lung-cancer cells, Ubc9 upregulation mediates the conjugation of SUMO2 to the protein Fatty-Acid SyNthase (FASN)—a key enzyme for de novo synthesis of fatty acids." (PMID 32781719, 2020). "FASN could be a key factor that involves in the AKT/ERK pathway activity, glucose metabolism and even altered the malignant phenotype in lung cancer cells." (PMID 31122252, 2019). "Indeed 3-V Biosciences will soon have a phase II clinical trial underway to investigate the use of a FASN targeting agent (TVB-2640) in treatment of ovarian, breast and lung cancer." (PMID 28086232, 2017). "In this study, we found a FASN-TGFβ1-FASN positive feedback loop in cisplatin-resistant lung cancer cells, but not in parental cells." (PMID 27765901, 2016). "Here we compare the effects of C75 and EGCG on lipogenesis (FASN activity), fatty acid oxidation (CPT activity), cellular proliferation, induction of apoptosis and cell signaling (EGFR, ERK1/2, AKT and mTOR) in A549 lung carcinoma cells." (PMID 22769244, 2012). "In lung cancer, inhibition of FASN using EGCG can be achieved without parallel stimulation of fatty acid oxidation and this effect is related mainly to EGFR signaling pathway." (PMID 22769244, 2012). "Importantly, inhibition of FASN by C93 did not induce FAO in H460 lung cancer cells at any dose level, compared to an approximate 80% increase in FAO upon treatment with C75." (PMID 35159223, 2022). "However, the level of total SREBP1 protein was not elevated obviously after PM2.5 exposure in either lung cancer cell lines based on western blot analysis, while its downstream proteins FASN and ACACA were clearly upregulated." (PMID 36496421, 2022).
lung carcinoma (continued). "Conversely, other works have pointed out that FASN activity has to be reduced in order to efficiently perform EMT in breast and lung cancer cell lines: a possible explanation may be that FASN activity is required to trigger EMT, while it has to be inhibited in order to complete the transition." (PMID 32932943, 2020). "In A549 human lung cancer cells, it was observed that apoptotic activity of EGCG‐treated cells was driven by a decrease in FASN activity rather than a decrease in FASN protein levels." (PMID 35243817, 2022). "The implication of FASN in increasing EMT and metastasis of various types of cancer cells has been reported previously, but its role in EMT/metastasis increase in cisplatin-resistant lung cancer cells has not been addressed." (PMID 27765901, 2016).
steatosis (85 papers, 2011 to 2026). Increased lipid within the cytoplasm of cells. "This treatment showed the key pathogenic features of NAFLD/NASH as enhanced steatosis, characterized by the upregulation of FASN and SCD1 and a concomitant reduction in β-oxidation-related pathways, as evidenced by a decreased expression of SIRT1 and PGC1α." (PMID 40649760, 2025). "Altogether, these lines of evidence demonstrate that TRIM56 kept hepatocyte steatosis in check by interacting with FASN and conjugated K48-linked ubiquitination chains to promotes the degradation of FASN." (PMID 38206764, 2024). "Increased FASN expression and activity have been consistently associated with steatosis-induced liver fibrosis and bleomycin-induced pulmonary fibrosis." (PMID 38051585, 2023). "TFEB knockdown substantially blocked the curative effect of hUC-MSCs on steatosis, as indicated by increased lipid droplets, elevated TG content, and upregulated expression of lipid metabolism-associated proteins FASN and SREBP1c." (PMID 41390431, 2025). "Moreover, in the mouse liver, TET-induced steatosis has been associated with upregulation of fatty acids elongases (Elovl 3, 5, 6) without altered expression of other genes involved in de novo lipogenesis, such as FasN, Srebp1c, and Pparγ." (PMID 24489787, 2014). "CVS also activates the FASN lipogenic pathway, which is strongly induced by oxidative and endoplasmic reticulum stress and leads to hepatic triglyceride accumulation and steatosis." (PMID 41566055, 2026). "SREBF1 and FASN were included as indices of hepatic lipogenesis, as CVS activates the SREBF1-FASN axis and promotes steatosis." (PMID 41566055, 2026). "Western blot analysis demonstrated that knockdown of PUM1 resulted in increased expression of sterol regulatory-element binding protein 1 (SREBP1), acetyl-CoA carboxylase 1 (ACC1), and fatty acid synthase (FASN) in steatosis hepatocytes." (PMID 40689527, 2025). "P.g. exacerbates 4NQO-induced OSCC by altering fatty acid metabolism, increasing FASN and ACC1, and promoting inflammatory cell infiltration; increased crestal bone loss, large tumors, and severe hepatic steatosis were observed in P.g.-exposed mice." (PMID 40924302, 2025). "On the other hand, two genes (CYP1A2 and FMO1) were downregulated in hepatotoxicity pathway, two genes (SREBF1 and FASN) in steatosis, one each in necrosis (IPO4) and phospholipidosis (SLC2A3) pathways." (PMID 38992651, 2024). "In a conductivity analysis, oxymatrine significantly reduced steatosis, decreased FASN and SCD1 expression, and increased SIRT1 expression and AMPK phosphorylation." (PMID 37570615, 2023). "Collectively, γ-MCA inhibits steatosis-induced peroxidative injury to ameliorate NASH by targeting FXR/SHP/LXRα/FASN signaling." (PMID 36904254, 2023). "Inhibition of fatty acid synthase (FASN) in human primary liver microtissues prevents the development of steatosis." (PMID 38022519, 2023). "In the present study, SATB2 upregulates FASN, an enzyme responsible for lipogenesis, steatosis, NAFLD and HCC." (PMID 35152538, 2022). "Nonalcoholic steatohepatitis is a disease vulnerable to HCC, which is accompanied by overexpression of FASN and severe steatosis." (PMID 36506561, 2022). "The ex-vivo human LMT model demonstrated that FASN inhibition decreases cellular triglycerides, a marker of steatosis or liver fat accumulation." (PMID 36123383, 2022). "There is strong genetic and preclinical evidence that FASN plays a critical role in the steatosis and hepatocarcinogenesis of the liver." (PMID 36506561, 2022). "The results from this preventative model indicate that FASN activity is required for the development of steatosis, pro-inflammatory activity, and fibrosis." (PMID 36123383, 2022). "FASN deletion in hepatocytes reduces steatosis and proliferation, which is in accordance with this process." (PMID 36506561, 2022).
steatosis (continued). "One study revealed a significant correlation of FASN expression with the degree of steatosis in primary human hepatocytes in vitro as well as in experimental murine models and the livers of patients with NAFLD in vivo." (PMID 34206460, 2021). "Research has revealed a significant correlation of FASN expression with the degree of steatosis in primary human hepatocytes in vitro as well as in experimental murine models and in the livers of patients with NAFLD in vivo." (PMID 34564583, 2021). "Branched chain amino acids including isoleucine have been found to alleviate steatosis by suppressing gene and protein expression level of fatty acid synthase." (PMID 32390870, 2020). "The protein levels of FASN were also elevated in the patients with steatosis and further elevated in the patients with NASH-fibrosis, whereas protein levels of both DNMT3A and SHP were not significantly changed in these patients compared to normal subjects." (PMID 33235221, 2020). "Altogether, our data indicate that celastrol effectively inhibits AKT/c-Met induced HCC development, mainly due to suppression of cell proliferation and FASN-induced steatosis." (PMID 35539339, 2018). "Caloric restriction reduces their hyperinsulinemia, and subsequently, hepatic fatty acid synthase level and steatosis, in parallel to inducing hepatic CEACAM1 levels and normalizing hepatic insulin extraction to the level of HCR." (PMID 28396653, 2017). "Circulating PCSK9 has also been found to be significantly associated with hepatic expression of SREBP‐1c and FASN, whereas PCSK9 mRNA levels have been found to be significantly correlated with steatosis severity and hepatic APOB, SREBP‐1c, and FASN expression." (PMID 28827398, 2017). "Histological examination using H&E, α-SMA, Masson, COL1A1 and FASN staining revealed that the degree of hepatic steatosis and hepatocellular ballooning in linc00907 knockdown mice was less severe than that in the control group, and lipid accumulation was also less pronounced." (PMID 38613803, 2024). "However, in our current study, hepatic ectopic expression significantly improves steatosis through degradation of FASN." (PMID 37249651, 2023). "Interestingly, Mx1-cre driver-mediated NIK deficiency in both hepatocytes and immune cells diminished hepatic inflammation and steatosis with reduced expression of lipogenic genes, such as FASN, ACC1, and SREBP-1c111." (PMID 34848839, 2021). "Therefore, the functional modulation of regulatory enzymes mediating the DNL pathway, such as ACC and FASN, has an important role in steatosis development." (PMID 34848839, 2021). "However, paradoxically, the liver specific deletion of the FASN gene exacerbates steatosis, while ACC1/2 inhibition reduces steatosis, but induces hypertriglyceridemia." (PMID 31959914, 2020). "Moreover, the abundant steatosis that resulted from FASN accumulation in the liver in AKT/c-Met mice was also attenuated." (PMID 35539339, 2018). "However, the regulation of a gene FASN gene indicates an inhibitory effect on steatosis." (PMID 38992651, 2024). "Thus, we consider that suppressed expression of lipogenesis-related enzymes (i.e., ACC1 and FASN) in the livers of pCAG DA-Nrf2 and pCAG Nqo1 treated RosaNIC/NIC::AdiCre mice is a part of the multifactorial mechanisms underlying improvement of steatosis in the setting of lipodystrophy." (PMID 37686150, 2023). "Interestingly, we found that protein levels of SREBP1 and ChREBP, 2 transcription factors that play critical roles in hepatic FA synthesis and steatosis, as well as FASN and ACC, 2 rate-limiting metabolic enzymes of DNL, were reduced in TRIM21-overexpressing livers compared with controls." (PMID 37937648, 2023). "While we have established APOA1 as a key functional regulator in OA-induced steatosis, the precise transcriptional regulatory relationship between APOA1 and downstream genes such as ACACA, FASN, CPT1, and APOB remains to be fully elucidated." (PMID 41463887, 2025).
steatosis (continued). "Consistent with the observed improvements in the hepatic lipid levels and steatosis, GWPH treatment markedly attenuated hepatic FASN expression in the HFCS-fed mice." (PMID 40573122, 2025). "Knockdown of PLIN5 in high-fat-diet (HFD) mice results in reduced steatosis and fibrosis in the liver, suppression of SREBP1 and its downstream fatty acid synthase (FASN),and inactivation of adenosine 5’-monophosphate-activated protein kinase (AMPK)." (PMID 39232826, 2024). "Increased expression of FASN, ACC, and PPARG was also observed in HepG2 cells transfected with miR-483, suggesting that miR-483 modulates the expression of steatosis/lipogenesis markers that leads to inhibition of cell steatosis." (PMID 36980601, 2023). "Compared with the control group, inulin reduced the steatosis lipid synthesis genes (CHREBP, Srebp-1c, FASN, and Scd-1) in mice fed a HFD and also significantly decreased the expressions of IL-6, IL-1β, and TNF-1α in the liver." (PMID 37554983, 2023). "Both enzymes are also critical for steatosis development in insulin-resistant states, and inhibitors of ACC and FASN are currently in clinical development for NASH." (PMID 37937648, 2023). "We found that 13-HODE induced hepatocyte steatosis, and that elevated cleaved SREBP1 and FASN levels were inhibited by si-Rictor." (PMID 38071367, 2023). "Similar to Cat overexpression, NAC decreased 13-HODE-induced hepatocyte steatosis and protein levels of activated SREBP1 and FASN." (PMID 38071367, 2023). "Negative regulation of PEPCK1 and FASN by TRIM21 reduces sustained gluconeogenesis and inhibits steatosis in hepatocytes, thereby significantly alleviating insulin resistance and glucose intolerance." (PMID 37249651, 2023). "Fatty acid synthase (FASN, also known as Fas), a key enzyme of fatty acid synthesis contributing to steatosis, catalyzes malonyl-CoA to palmitate." (PMID 37127639, 2023). "In another 12-week trial, 3 mg FASN inhibitor FT-4101 has been shown to reduce hepatic DNL and steatosis." (PMID 35956423, 2022). "To summarize, our results indicate that in steatosis the hepatic expression of DGAT-1, DGAT-2, FASN, and SREBP-1 increased significantly, and this increase was counteracted by the treatment with the nutraceutical formulation." (PMID 36135761, 2022). "Taken together, these primary human cell data indicate that FASN inhibition directly attenuates pathways of fibrogenesis and inflammation relevant to NASH, as well as reducing steatosis." (PMID 36123383, 2022). "FASN mRNA expression was higher in the LPNF-F2 offspring, suggesting a compensatory mechanism for energy homeostasis maintenance with low-grade steatosis (score 1)." (PMID 36704794, 2022). "Studies of PPARA liver expression in mice with steatosis in response to a high-fat diet show sex-differences: PPARA expression is increased in male rats, and FASN, which is directly downstream of PPARA, is also increased." (PMID 34861817, 2021). "Given these modulations of liver triglycerides and steatosis, we next measured hepatic mRNA levels of key lipogenic mediators involved in ALD-steatosis, including FASN, SREBP1-c, ACC1 and PPARγ, by qPCR." (PMID 33815111, 2021). "OMT significantly decreased the expressions of L-FABP, Plin2, FASN and SCD1 and increased Sirt1 expression and AMPKα phosphorylation in the liver of rats with steatosis." (PMID 32210812, 2020). "Transcription factors, fatty acid synthase, and fatty acid transporter genes play a major role in the process of FFA metabolism, triglyceride synthesis, and induction of steatosis." (PMID 33096687, 2020). "Additionally, increased steatosis was associated with enhanced hepatic expression of the lipogenic transcription factor sterol response element binding protein 1 (Srebp1c), and other known LXR target genes involved in fatty acid synthesis (fatty acid synthase, Fas)." (PMID 30673619, 2019).